EGFR (epidermal growth factor receptor)
Diseases named in the same sentence as EGFR in open-access papers (continued):
Sharing a sentence is not in itself a finding about the gene and the disease.
tumor (continued). "EGFR has been associated with tumor progression, poor prognosis, and low survival rates, making it an attractive target for tumor therapy." (PMID 39766327, 2024). "In an orthotopic GBM mouse model, the combination of oncolytic virus expressing IL15/IL15Rα and EGFR-CAR-NK cells causes a strong anti-tumor response." (PMID 38664743, 2024). "EGFR mAb associated PFS benefit was larger in those with KRAS WT tumours if they were aged 70 or younger (HRadj 0.68, p < 0.001) compared to those over 70 (HRadj 0.93, p = 0.465)." (PMID 38402342, 2024). "EGFR A763_Y764insFQEA and D761_E762insEAFQ mutations are associated with tumor sensitivity to conventional EGFR inhibitors." (PMID 38966170, 2024). "Tumor acquisition is vital and testing time for drivers is the current standard for the selection of treatment in EGFR-mutation positive advanced stage NSCLC." (PMID 39066920, 2024). "While circulating tumor DNA (ctDNA) in plasma has been utilized to detect EGFR mutations in NSCLC patients, the concordance rates between ctDNA and tumor tissues exhibit significant variation." (PMID 38982267, 2024). "The first attempt of the agnostic use of gefitinib is exemplified by its administration to a patient with EGFR-mutated renal cell cancer, which resulted in an objective tumor response." (PMID 38612902, 2024). "Previous studies also have reported that changes in EGFR mutations can occur over different time courses depending on a patient’s disease course and tumor burden." (PMID 39252953, 2024). "Preclinically, lazertinib showed a potent inhibition of tumor growth in cell lines and animal models possessing EGFR mutations, demonstrating effective pharmacodynamics." (PMID 38611728, 2024). "This is particularly concerning in advanced NSCLC patients with EGFR tumor mutations receiving sequential ICI therapy followed by osimertinib, as they experienced severe immune-related adverse events requiring hospitalization." (PMID 39664186, 2024). "As it is well known that IL-6 is critical in shaping tumor-associated inflammation and in promoting cell proliferation after being produced by EGFR-expressing macrophages, we decided to evaluate gene expression by qRT-PCR of this proinflammatory cytokine." (PMID 38613413, 2024). "A clinical study has reported that a combination therapy of osimertinib and cetuximab for a patient with an EGFR exon 20 mutation demonstrated efficient anti-tumor efficacy and that this promising result highlights the potential of this combination therapy." (PMID 39598567, 2024). "Although the clinical anti-tumor efficacy of osimertinib in NSCLC patients with EGFR-activation mutations has been proved, there is variability in the duration of response, with patients eventually developing acquired resistance." (PMID 39468027, 2024). "NIC, which calibrates the tumor’s iodine uptake to that of the thoracic aorta, mitigates interpatient hemodynamic variability, enhancing precise EGFR mutation status prediction." (PMID 38679659, 2024). "The oscillating patterns of tumor-specific mutations in ctDNA over time provided scientific justification for rechallenging anti-EGFR therapies, which were initially chosen based on clinical empiricism." (PMID 38792879, 2024). "Although our study was limited in size, we observed a trend where tumor organoids with KRAS mutations provoked a stronger immune response than those with epidermal growth factor receptor (EGFR) mutations." (PMID 39475596, 2024). "Exon 19 in-frame insertions constitute approximately 1% of EGFR mutations and render tumor sensitivity to conventional EGFR inhibitors." (PMID 38966170, 2024). "In this context, it has recently been found that the mutations involving EGFR-mediated signaling can be detected by the analysis of circulating tumor-derived genetic material present as DNA, tumor cells, or micro-vesicles as exosomes." (PMID 39000238, 2024).
tumor (continued). "These include the antibody-mediated detection of tumor-associated antigens such as the epidermal growth factor receptor EGFR and the epithelial cell adhesion molecule EpCAM in combination with near-infrared dyes." (PMID 38390268, 2024). "In a mouse xenograft model, the ability of KMP to successfully inhibit tumor growth through loss of hexokinase-2 expression and EGFR activity in cancerous tissues provided further evidence of the anticancer efficacy of the drug." (PMID 38339336, 2024). "Tumor recurrence, such as pleural involvement, was more prevalent in patients with the mutated EGFR gene." (PMID 39596989, 2024). "Among the tumors, 17% (n = 18) exhibited high PD-L1 expression (≥50% tumor proportion score), which was associated with a lower prevalence of common EGFR mutations (56% vs. 82%, p = 0.03) and a higher frequency of complex EGFR mutations (28% vs. 7%, p = 0.02)." (PMID 39509381, 2024). "Excessive activation of EGFR signaling pathways has been linked to inhibition of apoptosis and promotion of tumor growth." (PMID 38689087, 2024). "Third, we measured the prevalence ratio of EGFR mutations in the entire tumor region and compared it with VAF and histopathological patterns." (PMID 39358807, 2024). "Subsequently, TINCR upregulates the expression of the miR-503-5p target gene, EGFR (encoding epidermal growth factor receptor), by adsorbing miR-503-5p, ultimately promoting tumor development." (PMID 38172648, 2024). "It was demonstrated that the infiltration of CD8+ T cells was lower in EGFR-mutated tumors than in WT tumors, both in the immunocyte infiltration analysis of TCGA mRNA data and in the mIF analysis of tumor specimens." (PMID 39004699, 2024). "IDH mutation has emerged as a marker of better prognosis in low- and high-grade gliomas, in adults, and a mutation in EGFR, EGFRvIII, has also been studied as a biomarker related to tumour response and relapse as well as a potential therapeutic target." (PMID 38606198, 2024). "The preclinical studies demonstrated potent and selective pharmacodynamic activity against mutant EGFR forms, including the T790M mutation, in tumor models." (PMID 38611728, 2024). "An analysis of patients with an EGFR mutation showed that the presence of an L858R mutation in tumor tissue was an indicator of poor OS times." (PMID 39239557, 2024). "Tumor molecular profiling demonstrated an activating EGFR L858R mutation and an EGFR Y891D mutation at similar allele fractions." (PMID 38182677, 2024). "This study presents a predictive model integrating clinical parameters, computed tomography (CT) characteristics, and serum tumor markers to forecast EGFR mutation status in NSCLC patients." (PMID 39650554, 2024). "Future comparisons with other BsTEs targeting different antigens, such as Her-2 or epidermal growth factor receptor, will help elucidate the mechanism underlying the enhanced tumor-killing effects of BsTE:T." (PMID 39105814, 2024). "We confirmed the origin of the PDXs used for efficacy studies by comparing Sanger sequencing of driver EGFR mutation(s) in PDX tumor tissue with patient tumor tissue." (PMID 38276867, 2024). "Gene mutational sequencing of tumor tissue from biopsy specimens is the gold standard for detecting EGFR mutations." (PMID 38679659, 2024). "Immunoglobulin‐like transcript subunit 4 (ILT4), an inhibitory receptor of the immunoglobulin superfamily, plays a regulatory role in EGFR‐mutated NSCLC tumor cells by modulating the ERK/Akt signaling pathway." (PMID 39631794, 2024). "Genetic testing revealed that her tumor had mutations in epidermal growth factor receptor (EGFR) and the platelet-derived growth factor receptor β (PDGF-β)." (PMID 39749082, 2024). "DB-1310 suppressed tumor growth in a PDX model established with samples from osimertinib-resistant NSCLC patient harboring the EGFR Del19/T790M/C797S mutation." (PMID 38632563, 2024).
tumor (continued). "Genotyping of RAS mutations is routinely done on tumor tissue to predict drug resistance to anti-EGFR in patients with mCRC." (PMID 38642257, 2024). "Age (p = 0.036), GGO types (p = 0.005), tumor diameter (p = 0.039), and pathological types (p < 0.001) were significant predictors for EGFR mutation status." (PMID 39722087, 2024). "Together, these results suggest that loss of ZNRF/RNF43 elevates EGFR levels and signaling, promoting tumor development, sometime in conjunction with Wnt signaling activation and other times independent of Wnt signaling." (PMID 38260423, 2024). "Tumor molecular testing demonstrated EGFR mutations L833V and H835L, and the patient was treated with EGFR TKI osimertinib." (PMID 38196737, 2024). "Epidermal growth factor receptor (EGFR) tyrosine kinase inhibitors (TKIs) can specifically identify tumor cells with EGFR mutations and block the signal transduction pathway of tyrosine protein kinase to promote tumor cell apoptosis." (PMID 38414743, 2024). "Existing studies have shown that EGFR, a transmembrane protein, is closely associated with angiogenesis in the tumor region and tumor invasion, emerging as a crucial indicator for guiding targeted therapies." (PMID 39691475, 2024). "EGFR mutations activate a signaling pathway essential to cellular growth and differentiation, as well as to tumor progression and carcinogenesis." (PMID 39064005, 2024). "Prior to predicting EGFR mutations, we developed a model to classify tumor and non‐tumor regions in WSIs." (PMID 39358807, 2024). "Further studies reveal that mutations of receptor tyrosine kinases such as EGFR and c-Met lead to the over-activation of downstream signaling pathways, thus promoting tumor growth and metastasis." (PMID 39574469, 2024). "When tumor tissue harbors scarce tumor cells, analysis of driver mutations, particularly the EGFR mutation, in cell-free DNA is recommended." (PMID 39000058, 2024). "Due to its association with tumor progression, EGFR has become a prominent target for anti-cancer therapies." (PMID 39519855, 2024). "Serial circulating tumor DNA (ctDNA) analysis reveals decrease and clearance of the original activating EGFR and EGFR-T790M mutations which are prognostic of clinical outcomes." (PMID 38418463, 2024). "Detection of circulating tumor DNA in liquid biopsy (plasma) is increasingly used to identify targeted therapies for clinically actionable mutations, including EGFR mutations in NSCLC." (PMID 38593164, 2024). "In a recent TATTON trial, the combination therapy of savolitinib and osimertinib showed encouraging anti-tumor activity in patients with MET-amplified/overexpressed EGFR-mutated advanced NSCLC who had previously experienced disease progression on EGFR TKIs." (PMID 38892160, 2024). "For instance, EGFR mutations are frequently associated with increased SUVmax, reflecting higher metabolic activity in certain tumor subtypes." (PMID 39902124, 2024). "In early studies exploring tumor cells’ susceptibility to reovirus, the transfection of murine cells with epidermal growth factor receptor (EGFR) significantly enhanced both reovirus replication and virus-induced cytopathic effects." (PMID 39772250, 2024). "Numerous studies have demonstrated that these radiomic features correlate with tumor histological subtypes, genetic mutations (EGFR, KRAS mutations), and immune biomarkers (PD-L1 expression)." (PMID 39902124, 2024). "Of the 300 patients whose epidermal growth factor receptor (EGFR) mutational status was available, 24.3% had EGFR‐mutant tumor." (PMID 38622869, 2024).
tumor (continued). "According to the National Comprehensive Cancer Network (NCCN) guideline, all patients with metastatic CRC who are eligible for anti-epidermal growth factor receptor (EGFR) inhibitors should have the tumor tissue tested for BRAF and RAS mutations." (PMID 38763942, 2024). "EGFR gene amplification is detected in 57.4% of primary GBs, whereas the EGFR variant III (EGFRvIII) is a characteristic mutation that emerges later in tumor development." (PMID 38473776, 2024). "Of the remaining 56 tumor samples, all harbored common EGFR mutations, i.e., exon 19 deletion or p.L858R." (PMID 38464823, 2024). "Increased survival in patients with tumours in the upper lobes has been explained by the higher frequency of EGFR mutations that make these patients eligible for tumour-reducing therapy with tyrosine kinase inhibitors." (PMID 38439038, 2024). "In one study, the combination of EGFR-TKIs and cetuximab completely depleted phosphorylated and total EGFR in mice suffering from L8s8R/T790M erlotinib resistance, causing near-complete tumor regression." (PMID 38774882, 2024). "In cancer, EGFR is often continuously upregulated due to sustained production of EGFR ligands in the tumor microenvironment or as a result of a mutation of the EGFR itself, which blocks the receptor in a state of constant activation." (PMID 38664641, 2024). "Aberrant EGFR expression, such as gene amplification, overexpression of EGFR ligands, and mutations, all contribute to tumour growth and metastasis." (PMID 38773634, 2024). "It is important to remember that EGFR overexpression and mutations have been linked to poor prognosis, treatment resistance, tumor survival, and metastasis in a variety of cancer types." (PMID 38672455, 2024). "The association between AGRN, EGFR, and tumor necrosis further reinforces the role of AGRN in tumor progression and offers valuable insights for targeted cancer therapy." (PMID 39691475, 2024). "High PD-L1 expression, defined as staining in 50% or more tumor cells on immunohistochemistry, is significantly less prevalent in EGFR-mutated tumors (15.5%) compared to EGFR wild-type tumors (31%)." (PMID 39509381, 2024). "We also confirmed the apoptosis of CD8+ T lymphocyte by analysis of CD8α, TUNEL, and DAPI staining of tumor sections from LCBM patients with EGFR mutation." (PMID 38696655, 2024). "Numerous solid tumours have been found to harbour mutant forms of EGFR, with these mutations being associated with tumour progression, drug resistance, and patient survival." (PMID 38773634, 2024). "EGFR 20 ins mutations were more common in patients with normal serum tumor markers (3.83% vs. 1.05%, P = 0.037), and EGFR 21 L858R mutations were more frequent in patients with early stage disease (28.19% vs. 18.09%, P< 0.001)." (PMID 39364008, 2024). "Significant differences in PRSS prognostic model scores with respect to histological type, EGFR mutations and tumour staging further deepen our understanding of the intricate relationship between patient prognosis and disease characteristics." (PMID 39708330, 2024). "Associations between these cell cycle complexes and EGFR in the tumor microenvironment remain undetermined." (PMID 38772416, 2024). "α epidermal growth factor receptor (EGFR)-172 ADC is a tumor-targeted ADC constructed with the cGAMP analog IMSA172 linked to EGFR antibody via a cleavable Mc-Val-Cit-PABC linker." (PMID 38817608, 2024). "A phase II clinical trial on PD‐L1 inhibitors revealed that the objective response rate (ORR) was 12.2% among individuals with NSCLC and EGFR mutations who exhibited PD‐L1 expression in at least 25% of their tumor cells." (PMID 38659399, 2024). "Detection of EGFR mutation status typically requires invasive sampling of tumor tissue by surgery or biopsy." (PMID 38783331, 2024). "Expression of EGFR’s mutant EGFRvIII is frequently found in glioma cells and is associated with cell proliferation, tumor growth, treatment resistance, and poor prognosis." (PMID 39195222, 2024).
tumor (continued). "In these samples, 12 contained EGFR mutations (oncogenic drivers) across all tumor development stages." (PMID 38200551, 2024). "All the detected genetic abnormalities were heterozygous, and wild-type EGFR was found in normal lung tissue adjacent to the tumor, suggesting that these mutations are somatic." (PMID 38953007, 2024). "Further research is warranted to explore the potential association of the tumor microenvironment for such SCLC with EGFR mutations and outcrop suitable treatment strategies." (PMID 37436674, 2024). "Dysregulation of the EGFR pathway is linked to disease recurrence, tumour migration, as well as poor prognosis and lower survival rates in NPC patients." (PMID 39593139, 2024). "Abnormal EGFR activation causes sustained activation of genes associated with tumor proliferation and differentiation, thereby initiating and promoting tumor formation and progression." (PMID 39375945, 2024). "Studies have indicated that NSCLC patients with EGFR mutations (E19del/L858R) accompanied by a higher tumor mutational burden (TMB) tend to have a less favorable prognosis when treated with EGFR-TKIs than those with low TMB." (PMID 38238740, 2024). "In lung cancer, for instance, blood plasma can detect mutations in the EGFR gene when the tumor tissue is limited." (PMID 39063215, 2024). "Susceptibility testing indicated superior anti-tumor activity of second-generation EGFR-TKIs in these two PDOs, which was in concordance with historically clinical data for uncommon EGFR mutations." (PMID 38897205, 2024). "The EGFR gene with somatic SNVs is associated with wavelet.HHH.firstorder.Skewness which indicates the tumor pixel value distribution asymmetry on the CT images." (PMID 38811597, 2024). "EGFR-mediated tumor progression and resistance to EGFR TKIs were found to be linked to ROS-induced oxidative stress, stemming from mitochondrial dysfunction, NADPH oxidase (NOX) overactivation, and the aberrant expression of antioxidant enzymes." (PMID 38990147, 2024). "Tumor-associated viruses such as the Epstein–Barr virus (EBV) provided evidence that EVs released by EBV-infected cells packaged high levels of EGFR, suggesting an effect of EBV infection on the proliferation of neighboring cells via EVs." (PMID 39697631, 2024). "In a similar vein, certain studies have linked EGFR amplification and its nuclear localization to an advanced tumor stage and a lower chance of survival." (PMID 39452555, 2024). "Epithelial growth factor receptor (EGFR) is associated with tumorigenesis and tumor progression and is overexpressed in several oral malignant disorders." (PMID 38914986, 2024). "Blocking the EGFR pathway is linked to an increase in PD-L1 levels in tumor cells, leading to improved outcomes from PD-1/PD-L1 blockade therapy in cancers such as breast cancer and NSCLC." (PMID 38654302, 2024). "Further, gene set enrichment analysis (GSEA) also displayed several upregulation of the hallmark gene sets related to tumor progression and EGFR-TKI resistance, including epithelial-mesenchymal transition, angiogenesis, hypoxia, and TNF-α signaling via NF-κB." (PMID 39638994, 2024). "The objective was to assess tumor distribution, tumor volume reduction, and toxicity evaluation by monitoring weight loss in mice bearing EGFR-positive LS174T tumor xenografts." (PMID 38675202, 2024). "CRISPR/Cas9 can be used to specifically target, and knock-out, mutated or overexpressed oncogenes, such as MYC, KRAS, and EGFR, which drive tumor growth and progression." (PMID 39696697, 2024). "Intra-tumoural heterogeneity was seen in 28.6% of the study cohort (6 out of 21 tumours), which contained both EGFR-mutated and wild-type cells." (PMID 38539465, 2024). "A recent study has highlighted the role of TAM-derived IL-6, particularly in EGFR mutant NSCLC, revealing that IL-6 can augment the immunotherapy resistance of tumor cells with EMT-associated resistance to EGFR-TKI." (PMID 39286635, 2024).